NRAS (NRAS proto-oncogene, GTPase)
Diseases named in the same sentence as NRAS in open-access papers (continued):
Sharing a sentence is not in itself a finding about the gene and the disease.
cancer (continued). "Molecular characterization of CRC tumors has resulted in the identification of genetic alterations in cancer driver genes, such as KRAS, NRAS, BRAF, and ERBB2, which are now used to guide first‐line therapies." (PMID 37039257, 2023). "In contrast, dual inactivation of DUSP4 and DUSP6 selectively impairs growth in NRAS and BRAF mutant cells in cancer through hyperactivation of MAPK signaling." (PMID 37026010, 2023). "Interestingly, no NRAS mutation was found in poorly differentiated carcinoma (0/35)." (PMID 37277698, 2023). "The prognostic signature that we constructed consisted of seven cancer driver genes (CDKN2C, HRAS, IRAK1, LOX, MYCN, NRAS, and PABPC1)." (PMID 36017503, 2022). "To investigate this phenomenon, we analyzed CRISPR knockout data of cancer cell lines from the Achilles Project focusing on a dependency characterization of KRAS, NRAS, and HRAS29–31,34." (PMID 35046405, 2022). "The novel therapeutic development targeting KRAS-mutant cancers also works on discovery of pan-Kras inhibitors and proteolysis targeting chimeras (PROTAC) which avoid HRAS and NRAS." (PMID 36359850, 2022). "Of these common target genes of miR-495-3p and miR-543, NRAS, HMGA2, and EGLN1 present in KEGG cancer metabolic pathways stand out (p-value < 0.05)." (PMID 35645340, 2022). "Customized probes were designed to capture exonic regions of 141 genes selected for the panel, which was aimed for the detection of clinically actionable genetic variations in cancer, including KRAS, NRAS, BRAF, ALK, ROS1, KIT and EGFR." (PMID 35446881, 2022). "Kyoto encyclopedia of genes and genomes (KEGG) analysis showed that hsa_circ_0004099 was enriched in several cancer pathways, which were collectively enriched in four genes namely TCF7L2, NRAS, CTNNB1, and KRAS." (PMID 36399471, 2022). "LncRNA-SNHG15 regulated the expression of downstream genes including MYC, NRAS, BAG3, and ERBB3, which are closely related to cancer progression." (PMID 35617032, 2022). "The NRAS gene and its family KRAS and HRAS have been explained to be related to different types of cancers." (PMID 36430761, 2022). "While nearly 85% of RAS-driven cancers are KRAS mutants, HRAS and NRAS share approximately 82% to 90% of the amino acid (aa) sequence with KRAS, with the majority of variance occurring within the C-terminal region." (PMID 35923912, 2022). "Evidence for LOH as a frequent event in cancer initiation has been observed in model systems for all three RAS genes (HRAS, NRAS, KRAS)." (PMID 33924994, 2021). "RAS mutations are the most commonly found oncogenic alteration in human cancers, most frequently observed in KRAS (85%), and to a lesser degree in NRAS (12%) and HRAS (3%)." (PMID 34919052, 2021). "KRAS, NRAS proto-oncogene GTPase (NRAS), and HRas proto-oncogene GTPase (HRAS) are members of RAS proto-oncogenes family (RAS) and they play an important role in human cancers." (PMID 35048058, 2021). "Mutations on the G12/G13 positions in Ras proteins, including HRAS, KRAS, and NRAS, showed increased sensitivity to MEK inhibitors AZD6244 and PD-0325901 in multiple cancer types (BLCA, CESC, HNSC, PAAD, THYM, UCEC, and UCS)." (PMID 33741950, 2021). "Each harbors overlapping yet distinct sets of co-clustering phosphosites—KRAS p.S89/p.Y96, NRAS p.Y64, and HRAS p.Y32/T35/Y64/Y96—warranting further investigation into their potentially shared and distinct signaling functions across cancer types." (PMID 33875650, 2021). "Anti-proliferative activities of the fourteen GNF-7 derivatives on cancer cells harboring mtRAS (H358, AsPC-1, DU-145, SW480, HCT-116, MDA-MB-231, HT-29, OCI-AML3) and KRAS, NRAS-wt (U937 and MDA-MB-468) cells." (PMID 34956887, 2021).
cancer (continued). "The RAS oncogene family is comprised of three members, KRAS, NRAS, and HRAS, and plays an important role in normal development, but also for cancer development." (PMID 35048068, 2021). "Here we report a case of successive stages of bypass-mediated acquired resistance to erlotinib and crizotinib therapy, culminating in cancer with three different identifiable drivers including EGFR, MET, and NRAS." (PMID 34642436, 2021). "NRAS is a critical upstream regulator of MAPK/ERK signaling cascade, whose dysregulation is frequently involved in tumorigenesis in human cancers." (PMID 32210430, 2020). "In particular, diet-modulated miRNAs were able to target and interfere with several genes mainly involved in cancer signal transduction pathways (e.g., EGFR, RAC1, PLCG1, FOS, NRAS, SOS2, etc.)." (PMID 32911851, 2020). "Concomitantly, in cancer cells, TMPyP4-C14 decreases the expression of both KRAS and NRAS mRNAs and induces cell death upon photo-irradiation." (PMID 33198362, 2020). "Oncogene 5T4 is involved in the modulation of cell adhesion and is over-expressed in many types of cancer cells, as along with such oncogenes as MYC (proto-oncogene c-Myc) and NRAS (NRAS proto-oncogene, GTPase)." (PMID 31572192, 2019). "A genomic study performed in a large cohort of PTC from Saudi Arabia (n = 886), where thyroid cancer is the second most common cancer in women, showed a high prevalence of BRAF (59%), HRAS (2%), and NRAS (1%), similar to other cohorts." (PMID 31835496, 2019). "In cell‐based studies of NRAS‐ and KRAS‐mutant cancer cells, dabrafenib inhibited the NEK9 target CHK1, whereas vemurafenib did not." (PMID 29112787, 2018). "Here, we show that dabrafenib is more effective at inhibiting the growth of NRAS‐mutant and KRAS‐mutant cancer cell lines than vemurafenib." (PMID 29112787, 2018). "On the other hand, higher expression of HRAS, NRAS, APC, HFE, MMP9, and a high enrichment of MAPK/RAS, NFKB, and TNF signaling pathways are all evident in HLE cells as often seen in cancer." (PMID 30176945, 2018). "In agreement with this, our initial studies showed dabrafenib to be more effective at suppressing the growth of NRAS‐ and KRAS‐mutant cancer cell lines than vemurafenib." (PMID 29112787, 2018). "KRAS, NRAS, and HRAS are the 3 members of the RAS family of GTPases that are the most prevalent oncogenes in cancer progression and have similar cellular functions." (PMID 29568360, 2018). "Additional biomarkers currently being studied for application in cancer treatment include the PIK3CA, HER2, BRAF, ROS, RET, NRAS, MET, and MEK1." (PMID 29721208, 2018). "In summary, the absence of BRAF and NRAS mutations in every carcinoma displaying NIS membrane staining at immunohistochemistry supports the assumption that the genetic background of tumors may be of major importance to SLC5A5 expression as well as to NIS targeting to the basolateral membrane." (PMID 29298843, 2018). "The function of ZDHHC9 in cancers is unclear, although inactivation of ZDHHC9 can reduce leukemogenic effects through repression of oncogenic NRAS." (PMID 29285217, 2017). "We also observed several mutations in the MAP kinase signaling pathway (14% of tumors), involving KRAS, NRAS, BRAF, and MAP2K1 oncogenes across multiple cancer types including hematologic, lung, ovarian, duodenal, biliary, and colorectal." (PMID 29100271, 2017). "Starting from the cancer genes KRAS, NRAS and HRAS (that we will name RAS trio), similar in structure and mutational profile, we seek to extend this conservation to all the Ras superfamily members (in total, 133 different proteins belonging to the PF00071)." (PMID 26860319, 2016).
cancer (continued). "With the exception of the relatively well-known KRAS, HRAS and NRAS proteins, little is known about how the interactions of the other RAS human paralogs affect cancer evolution and response to treatment." (PMID 27713118, 2016). "Other large CNA genes gained or lost in the correct direction to drive cancer are PIK3R1 and CASP3 in BACA, and NRAS and CCND1 in CLAC." (PMID 26560147, 2015). "KRAS, NRAS, HRAS, BRAF, PIK3CA, PIK3R1 and PTEN are key cancer-related genes in the RAS/RAF and PI3K/PTEN signaling pathways." (PMID 25120700, 2014). "Due to the established role of NRAS, ITGA3 and STAT5 in cancer progression and cell death/survival, we focused on them." (PMID 24400121, 2014). "Similar findings for EREG high vs. low were seen when we examined complex cancer genotypes: a) KRAS+BRAF, both wild type vs. any mutant, b) KRAS+BRAF+PIK3CA+NRAS, all wild type vs. any mutant." (PMID 23374602, 2013). "Additionally, while the described studies specifically identify a requirement for Cdc42 in HRasV12-driven transformation, how Cdc42 might affect transformation resulting from the activation of other Ras proteins (i.e. KRAS and NRAS) commonly activated in human cancers remains to be explored." (PMID 22719838, 2012). "In subgroup analysis, Patients with KRAS or NRAS mutant tumors should not be treated with cetuximab alone or in combination with other anti-cancer drugs, as they have little chance of benefit and hence the exposure to toxicity and expense are not justified." (PMID 41262255, 2025). "Accordingly, BAY 11-7082 could be considered an effective inhibitor targeting NRAS, KRAS, and HRAS mutant cancer and serve as a promising candidate for more effective treatments tailored to all RAS-mutant cancers." (PMID 38982514, 2024). "Notably, Lgals3 which was up-regulated by TAA in non-cancer groups was also up-regulated in SB/AKT/c-Met + TAA (3.8-fold) and SB/AKT/NRas + TAA (4.1-fold)." (PMID 39254423, 2024). "Moreover, several confirmed gender-related carcinogenic genes exhibit completely different distributions in male and female cancer samples, such as PIK3CA, NF1, EIF1AY, IGF1R, NRAS, KDM5D, UTY, and PPP6C." (PMID 39541191, 2024). "Additionally, BAY 11-7082 inhibitor treatment leads to downregulation of several specific oncogenic signaling pathways in NRAS, KRAS, and HRAS mutant cancer cells." (PMID 38982514, 2024). "The targeted agents cetuximab and panitumumab, combined with chemotherapy, are an effective treatment for metastatic colon cancer, provided that certain mutations have not occurred in cancer cells (namely activating mutations in KRAS, NRAS or BRAF genes)." (PMID 37686636, 2023). "On the other hand, cell proliferation was not suppressed by miR-708 in cancer cells carrying wild-type NRAS or normal lung epithelial cells." (PMID 37083947, 2023). "It is noteworthy that the rs12028023 A‐allele specifically improved survival in patients with KRAS and NRAS mutant cancers, but not in those with BRAF mutant cancers, supporting a direct effect on the upstream RAS signaling pathway." (PMID 36790221, 2023). "Unlike other components of the MAPK pathway, such as KRAS, BRAF, and NRAS, MRAS has not been found to be mutated in human cancers, and perhaps this circumstance has excluded it from being an attractive anticancer target." (PMID 37996408, 2023). "Furthermore, these cancer pathways were jointly enriched in four genes, TCF7L2, NRAS, CTNNB1, and KRAS, which are mainly involved in cell proliferation." (PMID 36399471, 2022). "Currently, to the best of our knowledge, there is no targeted therapy that has yet been approved for NRAS-mutant cancer, although several inhibitors are under investigation." (PMID 35534592, 2022).
cancer (continued). "Our analysis of the DepMap data shows that MRAS knockout is well tolerated in cancer cell lines that are strongly dependent on SHOC2 for survival, consistent with the hypothesis that H/K/NRAS may substitute for MRAS in certain contexts." (PMID 35768504, 2022). "Remarkably, while enhanced MAPK1 activation associated with oncogenic mutations in upstream signal transducers (e.g., KRAS, HRAS, NRAS, and BRAF) is a common finding in cancer, MAPK1 mutations do not represent a major somatic event contributing to oncogenesis." (PMID 36394128, 2022). "When evaluated for mutation, 77.7% of cancers had BRAF V600E; 8.8% showed RET/PTC rearrangements; 4.4% were positive for PAX8/PPAr gamma and 9.1% had RAS mutations (H- and K-, no NRAS mutations were found in our series)." (PMID 34350538, 2022). "In addition, these four cancer pathways were jointly enriched in four genes, CTNNB1, TCF7L2, NRAS, and KRAS, mainly involved in cell proliferation." (PMID 36399471, 2022). "We hypothesize that our observed NRas-BRAF clusters and the NRas interactions with Grb2, NF1, and GPI in clusters could serve as novel targets for cancer therapy." (PMID 36304112, 2022). "All NRAS mutations at amino acid locations G12, G13, and Q61 have been identified in cancers and upregulate NRAS cycling; however, they impact NRAS activity differently." (PMID 36497424, 2022). "Blocking MEK, which is downstream of NRAS, has modest effects on these cancers, but MEK inhibitors alone do not provide clear clinical efficacy." (PMID 33921974, 2021). "As part of a study focused on overriding mtRAS, we expanded the application of this series of compounds to various cancer cells harboring KRAS-G12D (AsPC-1), KRAS-G12V (SW480, DU-145), KRAS-G12C (H358), KRAS-G13D (MDA-MB-231), KRAS-Q61L (HT-29), and NRAS-Q61L (OCI-AML3)." (PMID 34956887, 2021). "Toward this, we created a new Drosophila cancer model in which downregulation of Rbf1 is combined with downregulation of Pten and overexpression of Ras (Drosophila Ras85D is a single high-scoring ortholog of human KRAS, HRAS, and NRAS)." (PMID 33591981, 2021). "Of these comutation events, the NRAS mutations were mostly at codon 61, common for NRAS-driven cancers, such as skin cutaneous melanoma, and there was no detectable pattern of comutation between particular KRAS and NRAS alleles." (PMID 33753749, 2021). "Through analyses of these cells and of human oncogenic KRAS-, NRAS- and BRAF-driven cancer cell lines we identified that resistance to single MEK inhibitor and ERK inhibitor treatments arise rapidly but combination therapy completely blocks the emergence of resistance." (PMID 33924486, 2021). "On the other hand, the evaluation of genes involved in the RAS signaling pathway (including the NRAS, HRAS and KRAS genes), a pathway involved in several cancer types, did not reveal any variant in our cohort." (PMID 34284772, 2021). "NRAS is, together with KRAS, part of the GTPase family of genes that are often activated in cancer." (PMID 34615983, 2021). "In 2020, the FDA granted an expanded access program for the ERK inhibitor ulixertinib (BVD-523) for the treatment of cancer patients with abnormal MAPK pathways, including but not limited to those involving KRAS, NRAS, HRAS, BRAF, MEK, and ERK mutations." (PMID 34607583, 2021). "The apparent adverse interaction between NRAS and WT1 in AML and T-ALL might be due to these different roles of WT1 in cancer development and warrants further investigation." (PMID 34615983, 2021). "Importantly, in human cancers, PIK3CA/PTEN mutants and NRAS mutants provide two distinct therapeutic targets suitable for pharmacological intervention." (PMID 32210430, 2020). "A large-scale survey of cancer genomic and therapeutic databases has identified five candidate genes, namely PIK3CA, BRAF, NF1, NRAS, and PTEN, the targeting of which could be suitable for combination therapy with immunotherapy." (PMID 32483262, 2020).
cancer (continued). "The KRAS degrader specifically reduced proliferation of cells with mutant KRAS expression in 2D-adherent and 3D spheroid assays but did not modify the proliferation of cancer cell lines with mutant NRAS or HRAS nor of the RASWT cells HCC827 and MRC5." (PMID 32591521, 2020). "In fact, parental SW48 and LIM1215 cancer cells were significantly sensitive to cetuximab, panitumumab, SYM004 and MM-151 antibodies inducing growth inhibition, as expected being “quadruple wild type” for KRAS, BRAF, NRAS and PIK3CA genes." (PMID 31164152, 2019). "A link between the cell cycle effects of NEK9 silencing and CDK4 suppression was suggested by pharmacological studies in which the CDK4 inhibitors palbociclib and ribociclib also induced a G1‐phase cell cycle arrest and senescence in the NRAS‐ and KRAS‐mutant cancer cell lines." (PMID 29112787, 2018). "Each microdissected sample was also tested for cancer hotspot mutations on KRAS, BRAF and NRAS genes, and for the T790M EGFR resistanc e mutation, but no mutation was found." (PMID 29492209, 2018). "No cancer-associated EGFR gene mutation or copy-number variation, nor any KRAS, BRAF, NRAS hotspot mutations were found in any microdissected area." (PMID 29492209, 2018). "In human cancers, oncogenic mutations commonly occur in the RAS genes KRAS, NRAS, or HRAS, but there are no clinical RAS inhibitors." (PMID 30194290, 2018). "We sequenced specific exons of 16 cancer-related genes, including the most clinically relevant genes such as KRAS, NRAS, EGFR, BRAF, cKIT, as well as other targetable genes that are known to be somatically altered in solid cancers based on recent scientific and clinical literature." (PMID 28404952, 2017). "A missense variant in Epidermal Growth Factor EGF (p.Pro1096Thr), the upstream regulator of the NRAS/KRAS pathway, is predicted pathogenic by SIFT/PolyPhen-2 but has not been reported in association with cancer by the COSMIC or TCGA datasets." (PMID 29254223, 2017). "These defects were initially not retained in our filtering, because known cancer genes (NRAS, BCL10, TRIM33, RBM15) are also included in the same deletion and the minimal mutational frequency requirement was not satisfied." (PMID 28147343, 2017). "In particular, SW48 and LIM1215 cancer cells, that are wild type (WT) for KRAS, BRAF, NRAS and PIK3CA genes, and GEO cancer cells, that have a KRAS codon 12 mutation, are sensitive to the anti-epidermal growth factor receptor (EGFR) monoclonal antibody cetuximab." (PMID 28978118, 2017). "Deep-sequencing of 538 cancer-relevant genes was carried out in 57 HD-ALL patients lacking the common KRAS and NRAS codon 12 or 13 hotspot mutations and common B-cell ALL deletions." (PMID 27683039, 2016). "Targeted deep-sequencing of 538 cancer-relevant genes was performed in 57 HD-ALL patients lacking overt KRAS and NRAS hotspot mutations and lacking common B-ALL deletions to enrich for discovery of novel driver genes." (PMID 27683039, 2016). "Interestingly, we found that only NRAS and YWHAZ were elevated in cancer tissues compared to adjacent normal tissues." (PMID 27811373, 2016). "On the other hand, more information are available about NRAS and KRAS, in dog cancer." (PMID 26562302, 2015). "In many different human cancers, one of the HRAS, NRAS, or KRAS genes in the RAS family of small GTPases acquires an oncogenic mutation that renders the encoded protein constitutively GTP-bound and thereby active, which is well established to promote tumorigenesis." (PMID 25902334, 2015). "We have previously shown that palmitoylation is essential for NRAS leukemogenesis, suggesting that targeting RAS palmitoylation may be an effective therapy for NRAS-related cancers." (PMID 26715448, 2015).